AURKA (aurora kinase A)
Diseases named in the same sentence as AURKA in open-access papers (continued):
Sharing a sentence is not in itself a finding about the gene and the disease.
melanoma (continued). "Moreover, a triple drug combination including inhibitors of BRAF, MEK, and AurkA offered increased efficacy against melanoma cell growth; it might become a potential innovative treatment strategy." (PMID 26322273, 2015). "To determine whether the AURKA inhibitor MLN8237 inhibits the activation of AURKA phosphorylation on threonine-288 (T288) in melanoma cells, we treated Hs294T cells with MLN8237 for 3 days and performed Western blot analysis for phospho-AURKA (T-288) or phospho-AURKB (T-232)." (PMID 23180582, 2013). "The results indicated that high expression of PROM2, EGFR, AURKA, and low expression of IFNG, ARNTL, FBXW7 correlated with a poor prognosis of melanoma patients." (PMID 35692844, 2022). "The level of pPLK1 was significantly higher in S/G2 phases in both AURKA over-expressing cell lines, and similarly elevated in ATM defective and PPP6C mutant melanoma cells." (PMID 33993200, 2021). "For example, CDK1 was reported to interact with Sox2 and promote tumor initiation in human melanoma, CCNA2 and AURKA inhibitors are now available and has shown encouraging effect for treatment of melanoma." (PMID 31921860, 2019). "In melanoma, FOXM1 mediates AURKA transcriptional activation and expression, and activation of the mitogen-activated protein kinase/ERK pathway drives AURKA expression." (PMID 31334127, 2019). "An association was reported between MITF overexpression, partially regulated by AurkA, and MAPK pathway activation in controlling melanoma cell proliferation and migration." (PMID 30218391, 2018). "Cumulatively, based on these findings, we propose a model detailing the rationale for the dual targeting of AURKA and MAPK signaling in melanomas harboring the constitutively active BRAF(V600E) or NRAS (Q61R)." (PMID 26962685, 2016). "AURKA inhibitor MLN8237 has already entered phase III clinical trials for different cancers and phase-II trials in melanoma patients." (PMID 26962685, 2016). "AurkA inhibitor enhanced the effect of B-RAF and MEK inhibitors on melanoma cell growth in a 3D human skin reconstruction model." (PMID 26322273, 2015). "Moreover, for the first time, we have shown that a B-RAF, MEK and AurkA inhibitor triple drug combination offers increased efficacy against melanoma cell growth and might be considered as a potential treatment strategy for enhancing clinical response in melanoma." (PMID 25074438, 2014). "Moreover, for the first time, we have shown that a triple drug combination comprising of inhibitors of B-RAF, MEK and AurkA offers increased efficacy against melanoma cell growth and might be considered as a potential treatment strategy for enhancing clinical response in melanoma." (PMID 25074438, 2014). "Drug anti-tumor effects were further assessed using a 3D-human melanoma skin reconstruction model, in which tissues were incubated with serum-free medium containing control, B-RAF plus MEK inhibitor, MEK plus AurkA inhibitor or the triple combination." (PMID 25074438, 2014). "We observed that the levels of both AURKA and AURKB were significantly higher in synchronized melanoma cell lines than in synchronized normal melanocytes." (PMID 23180582, 2013). "It has been suggested that the combined inhibition of AURKA and FOXM1 could be considered a good strategy for patients with melanoma who are refractory to the combined use of BRAF/MEK inhibitors." (PMID 37259298, 2023). "Besides, AURKA and FOXM1 inhibition by either genetic knockdown or pharmacologic inhibitors impair melanoma growth and survival." (PMID 35039475, 2022).
melanoma (continued). "Additionally, AURKA and AURKB expression levels were significantly inversely correlated with T-cell markers in a dataset of melanoma samples derived from patients treated with anti-CTLA4 therapy." (PMID 33123754, 2021). "Using a set of melanoma samples derived from patients undergoing TIL therapy, we found that tumors that did not respond to treatment expressed significantly increased levels of AURKA compared to responding tumors." (PMID 33123754, 2021). "Several drugs were identified and ranked based on their potential to disrupt this signaling network; notably alisertib, a highly specific inhibitor of AURKA, which has been previously reported for its beneficial effect in combination with BRAF and MEK inhibitors in melanoma treatment." (PMID 34673281, 2021). "Strikingly, overexpression of LINC-PINT significantly reduced melanoma cells progression via downregulating the potential target genes CDK1, CCNA2, AURKA, and PCNA through recruiting EZH2 protein, which in turn mediated the trimethylation of H3K27 of promoter regions of target genes." (PMID 31921860, 2019). "Our data show that the AURKA inhibitor, MLN8237, significantly reduces melanoma tumour burden." (PMID 23180582, 2013). "We therefore validated that the gene expression of AURKA, CCNB1 and CDKN3 was upregulated upon UV-irradiation of Group 3 FM SF cultures and compared the expression of these genes in normal skin and melanoma tissue." (PMID 23371019, 2013). "Another finding was that inhibiting AURKA impaired melanoma growth and survival regardless of whether the melanoma cells are resistant to BRAF/MEK inhibitors." (PMID 35692844, 2022). "Interestingly, although MITF knockdown by itself failed to bear any significant impact on melanoma cell viability, its combination with AURKA-i greatly potentiated the latter's anti-proliferative activity." (PMID 26962685, 2016). "The mRNA level of ARNTL, AURKA, and IFNG in melanoma tissues were significantly higher than those in adjacent normal tissues." (PMID 35692844, 2022). "Although inhibition of AURKA in multiple myeloma induced both apoptosis and senescence, using the same inhibitor we did not observe significant apoptosis in response to MLN8237 in melanoma tumours in vivo." (PMID 23180582, 2013).
colon carcinoma (38 papers, 2007 to 2025). "High expression of AURKA is reported to be significantly associated with better survival in colon cancer." (PMID 37965456, 2023). "Particularly, AURKA, which is associated to colon cancer and was recently found to be over expressed also in hematological malignancies, as well as the drug resistant associated genes ABCB1, XRCC1 and CBR3 turned out to be affected." (PMID 35836575, 2022). "For example, PLT has the effect of inducing G2/M phase cell cycle arrest and mitochondrial-associated pathway apoptosis in HCT-116, HT-29, and SW-480 colon cancer cells by targeting kinase AURKA." (PMID 34684834, 2021). "We also tested the effect of dysregulated AURKA on chemosensitivity to the platinum drug and explored the underlying molecular mechanism in colon cancer." (PMID 32851091, 2020). "Genetic variations in the AURKA gene were also detected and associated with aneuploidy in human colon tumors and low penetrance CRC susceptibility factor." (PMID 25987188, 2015). "Examples include two genes identified through mouse mapping studies: AURKA, which shows allele-specific gains of the T91A allele in human colon tumors and PTPRJ, which shows allele-specific losses of the A1176C allele in human colon tumors." (PMID 20885788, 2010). "The results revealed a notable negative correlation between AURKA expression and the immunoinfiltration score in colon cancer tissues, suggesting that higher AURKA expression might be associated with reduced immune cell infiltration." (PMID 40290432, 2025). "As such, the amplification of a specific AURKA genetic variant was observed in colon cancer." (PMID 33050100, 2020). "We found that upregulated AURKA was associated with the improved prognosis of colon cancer patients; thus, we speculated that if AURKA increases chemosensitivity of platinum by increasing the genomic instability in colon cancer." (PMID 32851091, 2020). "Piperine’s targeting of particular proteins that are overexpressed in colon cancer cells—particularly AURKA (Aurora kinase A) and CDK1, which are important regulators of cell cycle progression—is what causes this synergy." (PMID 41164768, 2025). "The mechanism involves targeting Aurora kinase A (AURKA), inducing G2/M phase arrest in colon cancer cells, while regulating mitochondrial-related apoptotic pathways." (PMID 40786032, 2025). "AURKA overexpression contributed to oxaliplatin-induced death of colon cancer cells, while AURKA knockdown drastically reduced chemotherapy sensitivity of colon cancer cells to oxaliplatin." (PMID 35574421, 2022). "In most tumors, upregulation of KIF20A suggests a poor prognosis of patients, except for colon cancer, where it has been found that the AURKA upregulation in colon cancer suggests better prognosis of patients with colon cancer." (PMID 35574421, 2022). "Conversely, AURKA knockdown significantly weakened the chemosensitivity of colon cancer cells to Oxaliplatin42." (PMID 34907282, 2021). "AURKA was upregulated in various cancer types but only positively correlated with the prognosis of colon cancer patients." (PMID 32851091, 2020). "This study provides a possibility to use AURKA as a biomarker to predict the chemosensitivity of colon cancer to platinum in the clinic." (PMID 32851091, 2020). "Then we revealed that undermethylation of the AURKA gene and several transcription factors contributed to the upregulation of AURKA in colon cancer." (PMID 32851091, 2020). "To explore the mechanism by which AURKA was upregulated in colon cancer, we firstly analyzed the effect of methylation status on AURKA expression." (PMID 32851091, 2020). "This study provided a possibility to use AURKA as a biomarker to predict the chemosensitivity of colon cancer to platinum in the clinic." (PMID 32851091, 2020). "AURKA was elevated in colon cancer, but the upregulation of AURKA indicated better outcomes of colon cancer patients." (PMID 32851091, 2020).
colon carcinoma (continued). "We also identified that gene amplification in colon cancer patients can result in AURKA upregulation; however, its incidence rate was very low in colon cancer patients." (PMID 32851091, 2020). "We firstly constructed the stable cell lines with AURKA overexpression or knockdown and then assessed the effect of AURKA on the chemosensitivity of colon cancer cells." (PMID 32851091, 2020). "We revealed that AURKA was extensively elevated and predicted a poor prognosis in most of the detected cancer types, with an exception in colon cancer." (PMID 32851091, 2020). "Further study showed that undermethylation and upregulation of TFs potentially contribute to the elevated expression of AURKA in colon cancer at least partly." (PMID 32851091, 2020). "OS analysis showed that higher AURKA was correlated with a worse outcome of most of the cancer types, whereas it only indicated a favorable outcome in colon cancer." (PMID 32851091, 2020). "Of them, the expression of 85 TFs was positively correlated with the level of AURKA in colon cancer tissues according to the GEPIA correlation analysis." (PMID 32851091, 2020). "In fact, AURKA expression was shown to potentiate Ras-induced transformation, and it correlates with colon cancer progression." (PMID 28151959, 2017). "Recent reports showed that the upregulation of AURKA contributes to chemoresistance in a human cell line, pancreatic esophageal, breast and colon carcinoma cells." (PMID 25625960, 2015). "A 1998 study showed that overexpression of AURKA resulted in centrosome amplification, chromosomal instability and transformation in mammalian cells, including colon cancer cells." (PMID 25987188, 2015). "Other reports showed that pharmacological inhibition of AURKA with MLN8054 in colon cancer HCT-116 xenografts induces senescence in vivo." (PMID 25987188, 2015). "Our finding that AURKA increased the platinum chemosensitivity in colon cancer was different from the previous studies in other cancer types, which coincided with our finding that higher AURKA indicated better prognosis only in colon cancer but not in other cancers." (PMID 32851091, 2020). "In this study, we analyzed the expression state and regulation mechanism of AURKA in colon cancer." (PMID 32851091, 2020). "In colon cancer, the overexpressed AURKA is the contributor to chromosomal instability." (PMID 32851091, 2020). "Moreover, we demonstrated that AURKA overexpression promoted the death of colon cancer cells induced by Oxaliplatin, whereas knockdown of AURKA significantly weakened the chemosensitivity of colon cancer cells to Oxaliplatin." (PMID 32851091, 2020). "In addition, AURKA inhibition, using specific or pan Aurora kinase inhibitors, sensitized colon cancer cells to chemotherapy, TNF or TRAIL induced apoptosis as well as mitotic failure and cell death when inhibited along with SRC." (PMID 25987188, 2015). "Additionally, AURKA inhibition or knockdown was shown to induce senescence in multiple myeloma and colon cancer cells." (PMID 25987188, 2015).
colon carcinoma (continued). "To determine by another method whether AURKA amplification is correlated with resistance to Kinesin-5i, we measured AURKA DNA and mRNA copy number in a subset (n = 17) of the colon tumor cell lines by PCR." (PMID 19259408, 2008). "AURKA, on the other hand, demonstrated an absence of significant associations with the infiltration levels of any of the six analyzed immune cell types, suggesting a minimal direct impact on immune infiltration in the context of colon cancer." (PMID 40290432, 2025). "Moreover, overexpression of AURKA enhances Oxaliplatin-mediated killing of colon cancer cells." (PMID 34907282, 2021). "Finally, we demonstrated that AURKA might improve the prognosis of colon cancer patients by increasing the chemosensitivity of colon cancer to Oxaliplatin via inhibiting the DDR." (PMID 32851091, 2020). "Recent reports have shown that aurora kinase A (AURKA), IL6R, NUPR1, and DICER1 play important role in the development, progression, and metastasis of a variety of cancers including colon cancer." (PMID 36685857, 2022). "The result indicated that AURKA overexpression promoted the death of HCT116 and SW1116 colon cancer cells induced by Oxaliplatin, whereas knockdown of AURKA significantly weakened the response of colon cancer cells to Oxaliplatin." (PMID 32851091, 2020). "For instance, Tseng and colleagues found that AURKA enhances formation and aggregation of mutant Ras (RasV12) through regulation of RAS/MEK/ERK pathways and AKT phosphorylation in colon cancer." (PMID 25987188, 2015). "We demonstrate that AURKA and TPX2 are frequently amplified in cell lines from colon cancer of the chromosome instability (CIN) phenotype." (PMID 19259408, 2008). "In this study, we examined whether the combination of MK-5108 (AURKA inhibitor) and trametinib (MEK inhibitor) enhanced the antitumor effect for colon cancer cell lines." (PMID 40546348, 2025). "The combination of AURKA inhibitor and MEK inhibitor could be a novel strategy for RAS/RAF mutant colon cancer." (PMID 40546348, 2025). "This suggests that the abnormal expressions of AURKA, TIMP1, and NOX4 may play more pivotal roles in modulating the immune landscape during the oncogenesis and progression of colon cancer." (PMID 40290432, 2025). "Indeed, several research groups have reported the importance of Chr20 amplification in colon cancer, and attributed such effect to the location of multiple oncogenes such as BCL2L1, AURKA, TPX2, and SRC on this chromosome." (PMID 38593144, 2024). "Mechanistic studies of MV4-11 leukemia cells and HCT-116 colon cancer cells revealed that DBPR114 modulated FLT3 and AURKA/B targets inside the cells and induced the accumulation of multinucleated cells, which indicates mitotic checkpoint override through AURKB inhibition." (PMID 35062934, 2022).
colon carcinoma (continued). "Our data from the HCC cell lines and xenograft tumors further verified the mechanism of action of DBPR114 reported previously in AML and colon cancer cell lines, in which DBPR114 modulated FLT3 and AURKA/B inside the cells and induced the accumulation of multinucleated cells." (PMID 35062934, 2022). "Indeed, extracellular flux and carbon tracing analyses confirmed this notion, and inhibition of FAO or the electron transport chain along with Aurora kinase A blockage is synthetically lethal in GBM model systems and other recalcitrant solid malignancies, e.g., colon carcinoma." (PMID 34471141, 2021). "Importantly, recent reports indicated that AURKA is critical for tumorigenicity and chemoresistance in CRC stem cells, and suggested AURKA as a predictive marker for recurrence in stage III in colon tumors lacking microsatellite instability." (PMID 25987188, 2015).